TGFB1 (transforming growth factor beta 1)
Diseases named in the same sentence as TGFB1 in open-access papers (continued):
Sharing a sentence is not in itself a finding about the gene and the disease.
tumor (continued). "TGFB1 is also implicated in tumour development and progression, and both stimulatory and inhibitory roles have been described." (PMID 33761981, 2021). "Meanwhile, The TGFβ1 level in tumor stroma was positively associated with both PARP1 and cleaved-PARP1 in tumor by immunohistochemical analyses (P ≤ 0.001, R = 0.430; P = 0.064, R = 0.206)." (PMID 34095135, 2021). "TGFβ1-high levels in CAFs were associated with inhibition of growth, proliferation, antitumor immunity, and enhanced radiotherapeutic sensitivity and tumor immunity of tumor." (PMID 34095135, 2021). "We found that palladin loss phenocopies TGFβ1 inhibition and demonstrated that both palladin isoforms are important for CAFs to produce d-ECMs with tumor supportive functions." (PMID 33589694, 2021). "Platelet-specific Tgfb1-deficient mice showed reduction in tumor growth and platelet extravasation, compared to WT mice." (PMID 34987523, 2021). "The upregulation of Tgfb1 is particularly interesting in this context because Tgfb1 is known to induce the pro-tumoral properties of tumour-associated neutrophils." (PMID 34511060, 2021). "Yet, many studies have shown that low TGFβ1 expression in tumor stroma was associated with the promotion of cancer." (PMID 34095135, 2021). "Transforming growth factor β1 (TGFβ1) produced by cancer-associated fibroblasts (CAFs) in the tumor microenvironment has been pointed as a key player in the development of cSCC resistance to other therapies, such as chemotherapy." (PMID 34830768, 2021). "We previously showed that both BRAFV600E-PTC cells and tumor-associated macrophages contribute TGFB1 to the tumor microenvironment." (PMID 33890869, 2021). "Most of our identified differentially expressed genes, including TGFB1, display "chameleon-like" activity, i.e., the encoded proteins can exert opposite effects in different settings, e.g., different cell lines or tumor samples." (PMID 34906074, 2021). "The genomic DNA was extracted from 35 WT patients and 160 neoplasia-free children, and the TGFB1 polymorphisms were genotyped by polymerase chain reaction, followed by restriction fragment length polymorphism." (PMID 34722128, 2021). "In the current study, knockdown of TGFβ1 in CAFs was associated with greater proliferation and colony formation in co-cultured tumor cells." (PMID 34095135, 2021). "Since ASPN regulates GC metastasis through activation of EGFR and the ERK-CD44/MMP-2 pathway, it perhaps favourably associates with TGFB1 and activates the signaling pathway to promote tumor growth and progression." (PMID 34379688, 2021). "Soluble TGFβ1 impairs NK cell function in PDA patients and TGFβ signaling restrains CD8 T cell cytotoxicity, as CD8 T cells deficient in TGFβ signaling were more effective at lysing tumor cells in an adoptive transfer model into KC mice." (PMID 33584701, 2020). "To conclude, our findings indicate that intestinal nematode infection was associated with elevated TGFβ-1 levels and resulted in fewer, but larger, tumour nodules in the lungs." (PMID 32960348, 2020). "The role of TGFβ1 in tumorigenesis is complex and its tumor promoting functions are closely linked to the initiation of an EMT program." (PMID 33150300, 2020). "This collection of cytokines positively correlated with B2M, PD1 and TGFβ1 suggesting coexistence of pre-existing tumor-associated inflammation and immunosuppression." (PMID 32316978, 2020). "Among the TGFβ receptors, TGFβ1 expression is associated with higher clinical tumor stages and a lower 5-year survival rate." (PMID 32842503, 2020). "TGFB1 mRNA levels and TGF-β activation GES correlated with the strength of the tumor-associated macrophage GES." (PMID 30800658, 2019). "More precisely, resveratrol treatment decreases the levels of several oncogenic miRNAs targeting genes encoding tumor suppressors and effectors of the TGFβ signaling pathway, while increasing the levels of miR-663 targeting TGFβ1 transcripts." (PMID 31835371, 2019).
tumor (continued). "EC wall passage is assisted by TGFβ1 and tumor-associated macrophages (TAM), providing CFS1/MCSF1 and EGF." (PMID 31921628, 2019). "Tumor spheroids containing either control MSC or TGFB1-deficient MSC were highly enriched in spindle-like protrusions resulting from cells invading the hydrogel matrix." (PMID 29872504, 2018). "In contrast to serum TGF-β1 production and/or activation, tumor tissue expression of TGFB1 as mRNA or protein was generally associated with tumor progression." (PMID 30071009, 2018). "A study in human OSA patients found a significant association between high levels of tumour TGFβ1 and high histologic grade." (PMID 30477496, 2018). "PRDX2 is associated with tumor progression and has been implicated in the metastasis of cancers through its interactions with TGFβ1-induced epithelial-mesenchymal transition." (PMID 28765537, 2017). "This seemingly contradicts our findings, where both loss of SMAD4 and overexpression of TGFβ1 in the tumor microenvironment correlated with increased myeloid cell infiltration." (PMID 27270652, 2017). "TGFβ1, an important factor associated with tumor migration and invasiveness, was only downregulated following melatonin therapy alone." (PMID 28398226, 2017). "Mice deficient in TGFβ signalling in their epithelia showed enhanced disease progression, consistent with the loss of TGFβ1-dependent tumour suppression." (PMID 27515461, 2016). "Experimental evidence lends support to the observation that TGFB1 gene is frequently up-regulated in tumor cells and the loss of TGF-β signaling is proposed as a hallmark of carcinogenesis." (PMID 27835897, 2016). "Another marker that presented a significant association with OS when expressed in the tumor compartment was TGFB1." (PMID 27463005, 2016). "Recent reports suggest that tumor-derived OPN induces expression of CAF-associated markers in mesenchymal stromal cells through upregulation of transforming growth factor beta 1 (TGF-β1)." (PMID 26821678, 2016). "Although the source of TGFβ1 was not investigated in this study, others have shown that both tumors and tumor-associated cells contribute to TGFβ1-mediated anti-tumor T cell dysfunction." (PMID 27589814, 2016). "Recent work has also shown potential promise for the targeting of Tgfb1 (and other genes) in endogenous tumor-associated DC." (PMID 27589814, 2016). "TGFβ1 also promotes the formation of tumour-promoting M2 tumour-associated macrophages and N2 tumour-associated neutrophils." (PMID 27515461, 2016). "miR-155 delivery to tumor-associated DC in this model led to several changes in the transcriptome of these cells, including the silencing of Tgfb1 and other genes involved in the TGFβ1 signaling pathway." (PMID 27589814, 2016). "Among the members in this family, serum TGFβ-1 is a principal isoform in humans, and it is closely associated with the occurrence and development of tumor." (PMID 26003220, 2015). "Additional serum markers currently being explored include tumor-associated isoenzymes of gamma-glutamyl transpeptidase, urinary transforming growth factor-beta 1, and serum levels of circulating intercellular adhesion molecule-1." (PMID 29201680, 2015). "Among the members of this family, serum TGFβ-1 is a principal isoform in humans, and it is closely associated with the occurrence and development of tumor." (PMID 26003220, 2015). "Transforming growth factor-β1 (TGFβ1), which has been linked to cancer progression for its role in the tumor microenvironment, and which participates in exosome-mediated biological functions, was 6-fold more abundant in nano-sized versus large EVs." (PMID 25857301, 2015). "The same group found tumor exosomes derived from myeloid-derived suppressor cells (MDSCs) and Clayton and colleagues found tumor exosomes derived from mesothelioma to express (membrane-associated) Transforming Growth Factor-β (TGFβ1)." (PMID 24460816, 2014).
tumor (continued). "Reduction in tumor volume was associated not only with promotion of tumor apoptosis but also with suppression of the pro-angiogenic molecules HIF1α, VEGFα, IL-8 and TGFβ1 and with inhibition of tumor angiogenesis." (PMID 25275595, 2014). "XPO4 in cancerous liver tissue and TGFβ1 in paracancerous liver tissue were positively associated with tumor differentiation." (PMID 23251252, 2013). "It is not clear if the tumors with elevated ligand expression represent a distinct subset of tumors, but we and others have linked decreased or loss of TGFβ1 expression with increased risk for malignant progression in the 2-stage skin carcinogenesis model." (PMID 23326666, 2012). "Our results provide evidence that enhanced metastasis and decreased survival of tumor bearing SPARC-deficient mice is a result of aberrant activation of TGFβ1." (PMID 22348081, 2012). "In contrast, over-expression of TGFβ1 has been described in several tumors in vivo and has also been associated with tumor progression and metastasis." (PMID 21483670, 2011). "Although several groups demonstrated that increased TGFβ1 was associated with more aggressive tumour behavior and poorer survival, other authors reported the absence of correlation between disease progression and TGFβ1 immunostaining or mRNA level." (PMID 16404434, 2006). "Consequently, the TGFβ1/Smad2/3 signaling pathway drives the transdifferentiation of GC-MSCs into cancer-associated fibroblasts (CAFs)-promoting stromal remodeling and tumor aggressiveness." (PMID 42114147, 2026). "Transforming growth factor beta 1 (TGF-β1) signaling has been implicated in hepatic fibrogenesis and tumor-associated remodeling and may co-vary with disturbances in lipid trafficking." (PMID 41677755, 2026). "Apigenin inhibits ECM production in transforming growth factor-beta 1 (TGF-β1)-stimulated cardiac fibroblasts by modulating specific signaling pathways, which may have implications for tumor-associated fibrosis." (PMID 40563308, 2025). "TGFB1 induces the infiltration of Tregs and cancer-associated fibroblasts, thereby inhibiting the cytotoxic T cell and NK cell killing, creating an immunosuppressive tumor microenvironment." (PMID 40386043, 2025). "Transforming growth factor-beta 1 (TGFβ1)-induced oxidative stress has been implicated in transforming normal fibroblasts into CAFs, which secrete additional exosomes containing miRNAs that further modulate the redox balance and tumor progression." (PMID 40427384, 2025). "Conversely, TGFβ1 may also elicit tumor promotion in late-stage cancer cells with loss of its inhibitory functions that promotes tumor angiogenesis, metabolic flexibility, EMT, and evasion of drug-induced apoptosis." (PMID 41614767, 2025). "In the high-risk group, we observed a substantial upregulation of several immune-suppressive and regulatory molecules, including PD-L1 (CD274), CD276, TIM-3 (HAVCR2), LAG3, and TGFB1, all of which are associated with an immunosuppressive tumor microenvironment." (PMID 40959429, 2025). "TGFβ1, a cancer-associated cytokine, has a dual role in tumorigenesis and tumor development." (PMID 38688896, 2024). "Thus, the concentration of the cytokines CCL2, CCL5, CCL18, and TGFB1 in the CSF was associated with tumor size in patients." (PMID 39272860, 2024). "However, a declining trend in Ifng expression was observed in the late-stage (5wk) ICI-resistant mice, concomitant with an increase in Transforming Growth Factor Beta-1 (Tgfb1) associated with tumor epithelial–mesenchymal transition (EMT)." (PMID 38805119, 2024). "In the stroma, TGFβ drives the transformation of CAFs into highly contractile myofibroblasts that express αSMA and secrete substantial quantities of FN and collagen I. Disrupting TGFβ1 is linked to reduced macrophage polarization to M2 and associated with reduced tumor growth." (PMID 38660622, 2024). "Inhibition of TGFβ1 causes a robust antitumor immune response and tumor regression." (PMID 38152616, 2023).
tumor (continued). "Also, significant alterations in genes associated with tumor cell invasion were detected, such as significant upregulation of TGFβ1, ROAR, DAB2, BMP6, NOS2, PLXN2, and CADPS exhibited, and significant downregulation of TCF4." (PMID 38003292, 2023). "Abundance of transforming growth factor beta 1 (TGFB1), a growth factor associated with multiple oncogenic pathways such as tumor proliferation, EMT, angiogenesis, immune evasion, and metastasis, was elevated in the Progenitor-cell infiltrated cluster and well-correlated with the Sunitinib response." (PMID 37460463, 2023). "Tumor associated macrophages were enriched in M2 genes, Arg1, Il1rn, and Tgfb1." (PMID 35600339, 2022). "It is tempting to speculate that loss of decorin during tumor progression may increase TGFβ1 bioavailability in the tumor microenvironment." (PMID 35435599, 2022). "This may suggest that the reduction of the TGFB1 expression observed in the most advanced neoplasms is associated with loss of control over this process." (PMID 35798776, 2022). "Deficiency of the TGFβ1 or TGFβR1 reduced half of the tumor size of orthotopic ovarian cancer." (PMID 34722319, 2021). "TGFB1 functions to promote transformation of cells and is associated with tumor invasion." (PMID 34771552, 2021). "For instance, our data showed that TGFβ1 gene encoding TGF-β, which is known to inhibit T effector cell functions, promote Treg survival/differentiation, and support tumor invasion and metastasis, was expressed at higher levels on CD8+ TILs compared to CD4+ TILs." (PMID 33916009, 2021). "Consistent with these associations between TGFB1 variations and clinicopathological characteristics, the progression risk during ADT was associated with TGFB1 genotypes, suggesting that TGFB1 genotypes were associated with PFS through unfavorable tumor characteristics." (PMID 34113577, 2021). "The TGFβ1 level (lower or higher than the median) in tumor stroma was positively associated with that of PD-L1 in tumor stroma and tumor (P ≤ 0.001, R = 0.428, 0.388), and CTLA4 in tumor stroma (P ≤ 0.001, R = 0.350), but not CD8 or FoxP3 in tumor stroma (P = 0.970; 0.249, respectively)." (PMID 34095135, 2021). "TGFB1 polymorphism rs1800472 may confer greater activity to TGF-β1 in the tumor microenvironment, favoring PTC aggressiveness." (PMID 33905626, 2021). "Finally, the GG genotype of TGFB1 rs6957 associated with lower tumor TGFβ levels (p = 0.03) and less CD163+ macrophages (p = 0.01), but did not modulate patients’ survival." (PMID 33648463, 2021). "For example, TGF-β1, a secreted cytokine encoded by TGFB1 which is located on chromosome 19q, could enhance immune cell infiltration in tumor." (PMID 34335194, 2021). "Interfering with growth inhibition by exogenous TGFβ1 enhances mitotic activity, eventually resulting in a hyper-proliferative state that may have a role in early tumor development prior to mutational inactivation of Smad signaling." (PMID 33802809, 2021). "Persistence or increase of IL17 and an increase of TGFβ1 (consistent with an ongoing response that could be either anti-tumor or tolerizing depending on the TGFβ1 dominance) was associated with intermediate survival." (PMID 32316978, 2020). "For example, the single-nucleotide polymorphism (SNP) 509C/T on the TGF-β1 gene promoter region can influence the infiltration of DCs at the invasive margin of the tumour, with the T-allele of the TGFB1 -509C/T SNP having a protective factor for the development of CRC." (PMID 33114183, 2020). "Interestingly, the TGFβ1 pathway has been implicated in metastatic processes and dramatically impacts the ability of tumor cells to spread throughout the body." (PMID 33150300, 2020). "In addition to G-CSF, cytokines encountered by MDSCs in the TME include most prominently TGFβ1 derived from various cell types including tumor cells per se, tumor-associated macrophages (TAMs) of the M2 phenotype, epithelial cells and fibroblasts." (PMID 33233675, 2020).
tumor (continued). "Finally, strong association between elevated expression of TAGLN and TGFβ1 gene expression in CRC tumor samples and poor prognosis further support the association between TAGLN and advanced CRC disease." (PMID 32393769, 2020). "Thus, platelets require GARP to produce activated TGFβ and appear to be an important source of both systemic and tumour-associated TGFβ1 mediating immunosuppression." (PMID 31438626, 2019). "Based on these reports, we hypothesized that TGIF1 deficiency or downregulation is an alternative mechanism underlying the late-stage TGFβ1/Smad-mediated tumor progression and metastasis." (PMID 31109321, 2019). "In vivo similar results were observed, along with increased pSmad2/3 signalling in the stroma of collagen-7 deficient SCC tumours, implying that collagen-7 acts as a TGFβ suppressor, and consistent with αvβ6-dependent TGFβ1 activation inducing fibroblast to myofibroblast transition." (PMID 31438626, 2019). "Interestingly, this tumor cell population increment was detected in co-cultivation with either control MSC or TGFB1-deficient MSC." (PMID 29872504, 2018). "Interestingly, expression of most genes was attenuated at 8 weeks of age in pre-metastatic lungs in both Ikkβ-proficient and deficient mice and only Tgfb1 was higher expressed in both genotypes compared to tumor free and metastatic animals." (PMID 29682184, 2018). "In the tumor stroma, TGFβ1 gets secreted by tumor‐associated macrophages and CAFs." (PMID 30004628, 2018). "Interestingly, only a subset of these different tumor types showed significant associations between TGFB1 expression and stromal genes, and only a further subset of these showed associations with the T cell signature or, in turn, mutational load." (PMID 28448494, 2017). "A skin carcinogenesis study suggested differential functions for each TGFβ isoform in epidermal carcinogenesis: TGFβ1 was associated with a more differentiated state, TGFβ2 was associated with highly malignant and invading cells, and TGFβ3 was linked to tumor stroma." (PMID 28758950, 2017). "TGFβ1 expression is associated with local tumor relapse and survival of NPC patients." (PMID 28423621, 2017). "Therefore, we must consider it likely that, in clinical studies in which poor overall survival has been linked to the over-expression of αvβ6, TGFβ1 activation by αvβ6 is a tumour-driver." (PMID 27515461, 2016). "Indeed, decreased expression of TGFβRI/II receptors or mutations in these proteins that abrogate TGFβ1 signaling in tumor cells have been observed in many cancer types." (PMID 27589814, 2016). "This review focuses on the role of TGFβ1 dysregulation in cancer-associated immune suppression and highlights how our current understanding of TGFβ1-mediated tumor immune escape is driving therapeutic interventions to target this pathway in the treatment of cancer." (PMID 27589814, 2016). "Once tumour cells develop mutations that render them refractile to the growth-suppressive effects of TGFβ1, then the cytokine can become tumour-promoting by acting directly on the tumour cells to drive an invasive programme but also indirectly by promoting a tumour-permissive microenvironment." (PMID 27515461, 2016). "It implicated that the malignant tumour cells up-regulated TGFB1 expression." (PMID 26703884, 2015). "The mechanisms underlying the reduced TGFBR2 expression in tumours and the differentially regulated TGFB1 and TGFB3 expression by malignant and premalignant tumour cells may also have potential clinical implications that need to be further explored." (PMID 26703884, 2015). "Is has been hypothesized, that TGFBR2 repression is responsible for most of the tumor associated TGFβ1 resistance observed in vivo." (PMID 23951322, 2013). "Moreover, TGFβ1 can induce apoptosis, a process associated with tumour suppression, promote replicative senescence and exhibit negative regulation of angiogenesis." (PMID 16404434, 2006).